CCT2 (chaperonin containing TCP1 subunit 2)
Diseases named in the same sentence as CCT2 in open-access papers (continued):
Sharing a sentence is not in itself a finding about the gene and the disease.
lung carcinoma (5 papers, 2017 to 2025). "Higher levels of CCT2 in tumors from lung cancer patients were also associated with decreased survival." (PMID 29299146, 2017). "Increased expression of CCT2 in tumors obtained from patients with lung cancer is likewise correlated with diminished survival rates." (PMID 41203126, 2025). "All lung cancer subtypes examined had significantly higher levels of CCT2 as compared to normal tissue." (PMID 29299146, 2017). "To investigate if CCT2 levels correlated with survival in lung cancer patients, we used the publicly available Kaplan-Meier plotter database to generate survival data in all lung cancer patients that expressed high levels of CCT2 mRNA." (PMID 29299146, 2017). "We selected SqCLC and SCLC to study in greater detail because together, these two lung cancer types represent 35%-45% of all cases and both scored significantly higher than normal tissue for CCT2." (PMID 29299146, 2017). "We next assessed the levels of CCT2 in various subtypes of lung cancer by evaluating staining intensity in 236 tissue microarray cores containing cases of adenocarcinoma, carcinoid, SCLC, and squamous cell lung carcinoma (SqCLC)." (PMID 29299146, 2017). "We found that there was a statistically significant correlation (p = 0.0031) between decreased survival of grade III lung cancer patients and CCT2 expression, with a 30-month difference in survival between the higher expression patient cohort and the lower expression patient cohort." (PMID 29299146, 2017). "This was most notable in the detection of breast and lung cancer cells spiked into blood that were CK dim but CCT2 positive and not leukocytes." (PMID 35749519, 2022). "Essentially, CCT2 levels were higher than normal lung in these lung cancer subtypes and independent of stage or grade." (PMID 29299146, 2017).
Alzheimer disease (4 papers, 2022 to 2025). A progressive, neurodegenerative disease characterized by loss of function and death of nerve cells in several areas of the brain leading to loss of cognitive function such as memory and language. "Among all TRiC subunits, CCT2 has been implicated in modulating the aggregation of various proteins associated with Alzheimer’s disease, tauopathies, and polyglutamine diseases." (PMID 40693240, 2025). "First, bioinformatics database analysis revealed that CCT2 was significantly downregulated in patients with Alzheimer’s disease and associated with autophagic clearance of β-amyloid." (PMID 36704351, 2022). "In Alzheimer’s disease, CCT2 was part of a gene set used to develop a diagnostic profile." (PMID 35602608, 2022). "A recent study highlights the crucial role of CCT2 in neurodegenerative diseases, particularly exploring its significance in Alzheimer’s disease (AD) via multi-omics analysis." (PMID 39478698, 2024). "Chaperonin containing TCP1 subunit 2 (CCT2) is essential in various neurodegenerative diseases, albeit its role in the pathogenesis of Alzheimer’s disease (AD) remains elusive." (PMID 36704351, 2022). "The logistic prediction model with 13 key genes, such as CCT2, screened in this study better predicts Alzheimer’s disease occurrence (AUC = 0.9671) and is a favorable candidate for predicting potential biological targets of Alzheimer’s disease." (PMID 36704351, 2022). "This study aimed to evaluate the role of CCT2 in Alzheimer’s disease." (PMID 36704351, 2022). "Our findings suggest that low CCT2 expression may be responsible for the autophagy suppression in Alzheimer’s disease, providing an accurate explanation for its pathogenesis and new targets and small molecule inhibitors for its treatment." (PMID 36704351, 2022). "Aberrant expression of other CCT subunits, like CCT2, also correlated with Alzheimer’s disease or Parkinson’s disease and could be used as biomarkers to assist with neurological disease prognosis and management." (PMID 35602608, 2022).
gall bladder carcinoma (4 papers, 2013 to 2019). "The positive expression of CCT2 in gallbladder carcinoma is associated with TNM stage and lymph node metastasis." (PMID 32117430, 2019). "Our study suggests that positive expression of CCT2 or PDIA3 is associated with tumor progression and the clinical behavior of gallbladder carcinoma." (PMID 23782473, 2013).
glioma (4 papers, 2020 to 2025). A benign or malignant brain and spinal cord tumor that arises from glial cells (astrocytes, oligodendrocytes, ependymal cells). "We previously reported significantly higher CCT2 and CCT7 levels in GBM neurosurgical aspirate-EVs compared to GII-III glioma, with analogous transcript expression levels and DNA copy numbers reported for CCT2 and CCT7 in GBM tissue compared to normal brain in TCGA datasets." (PMID 32635403, 2020). "Moreover, analyses of gene expression and DNA copy number showed that CCT2, CCT3, CCT5, CCT6A, and CCT7 are upregulated in GBM compared with normal brain tissue, while CCT2, CCT3, CCT5, CCT6A, and CCT8 display higher copy numbers than in low-grade gliomas." (PMID 41516249, 2025). "In particular, EVs obtained from CUSA (cavitron ultrasonic surgical aspirator) samples during GBM surgeries showed higher levels of all eight CCT subunits compared with those from low-grade gliomas, with CCT1, CCT2, CCT6A, and CCT7 being the most prominently upregulated." (PMID 41516249, 2025).
prostate carcinoma (4 papers, 2017 to 2026). A carcinoma that arises from epithelial cells of the prostate gland. "This study reveals that CCT2 promotes lipid metabolic reprogramming and tumor progression in prostate cancer by cooperating with EIF3F to stabilize FASN, highlighting the CCT2-EIF3F-FASN axis as a potential target for metabolic intervention." (PMID 42231807, 2026). "Because increased stage indicates higher severity of disease and poorer prognosis, we also analyzed CCT2 levels in prostate cancer by stage and observed a trend of increasing CCT2 staining with increasing stage." (PMID 29299146, 2017). "In the current study, in addition to HCC and prostate cancer, we also found that CCT2 was increased in SCLC and in advanced stages of SqCLC." (PMID 29299146, 2017). "In addition, the expression levels of three proteins—TUFM, and HNRNPH3 from the DHT-specific proteome, and CCT2 from the FSK-specific proteome—were related to the progression-free interval in prostate cancer patients." (PMID 34680521, 2021). "To determine whether CCT2 was elevated in other cancers, we evaluated CCT2 protein levels in several human tissue microarrays (TMAs) for lung, colon, hepatocellular, and prostate carcinomas by immunohistochemistry (IHC)." (PMID 29299146, 2017). "Our own published studies provided evidence that CCT2 is significantly overexpressed in invasive ductal breast carcinoma and in triple-negative breast cancer (TNBC) cell lines, like MDA-MB-231, as well as prostate cancer cell lines." (PMID 29299146, 2017).
gallbladder cancer (3 papers, 2019 to 2022). "In gallbladder cancer, it was shown by multifactorial analysis that a positive CCT2 expression was negatively correlated with low postoperative patient survival and positively correlated with high mortality." (PMID 36119498, 2022). "In gallbladder cancer, positive CCT2 expression was negatively correlated with low postoperative patient survival and positively correlated with high mortality." (PMID 36119498, 2022).
retinal degeneration (3 papers, 2019 to 2023). Degeneration of the retina. "Our results here are consistent with the essential chaperone function of CCTs during the biogenesis of photoreceptor cilia in mice, which is supported by the identification of mutations in CCT2 causing retinal degenerations in LCA patients." (PMID 37427378, 2023). "Similar to our cct5 mutant, cct1, cct2, cct3, cct4 and cct8 mutant zebrafish show retinal degeneration, suggesting that the cct5/tcf7l1a double mutant phenotype is due to abrogation of TRiC chaperonin function, a conclusion supported by cct3 knockdown in tcf7l1a mutants." (PMID 30777146, 2019).
breast invasive carcinoma (2 papers, 2021). "CCT2 is also genetically altered in invasive breast cancer along with other 12q15 oncogenes, the percent of which varies depending on the study and availability of samples." (PMID 33996588, 2021).
breast tumor (2 papers, 2019 to 2021). "Using 3D cultures to model breast tumor growth we observed increased spheroid formation upon CCT2 over expression, as evidenced by multiple and larger spheroids, and loss of tight cell contacts that support spheroid structure when CCT2 was depleted." (PMID 33996588, 2021). "For instance, the homolog of one of our identified top-hits, CCT2, along with TCP1, has recently been linked as a driver mutation in breast tumor formation." (PMID 31270132, 2019).
cholangiocarcinoma (2 papers, 2017 to 2021). A carcinoma that arises from the intrahepatic biliary tree (intrahepatic cholangiocarcinoma) or from the junction, or adjacent to the junction, of the right and left hepatic ducts (hilar cholangiocarcinoma). "In liver carcinomas, CCT2 levels were higher in both subtypes analyzed (HCC and cholangiocellular carcinomas) as compared to normal hepatic tissue." (PMID 29299146, 2017).
colorectal adenocarcinoma (2 papers, 2019 to 2025). The most common type of colorectal carcinoma. "The colorectal adenocarcinoma dataset revealed that the increased expression of CCT2 resulted in a significantly decreased disease-free survival." (PMID 30578123, 2019). "It was found that elevated expression of RPL31, CCT2, RPL17, and NUP85, as well as downregulation of NUP98, CDC37, DNM2, and SNRPN resulted from corresponding μ-ASOs treatment, correlating with improved survival in colorectal adenocarcinoma patients according to the TCGA database." (PMID 41373892, 2025).
gastric cancer (2 papers, 2019 to 2024). A primary or metastatic malignant neoplasm involving the stomach. "In gastric cancer, Tspan31 was found to be upregulated in tumor tissues, and silencing Tspan31 effectively inhibited migration and proliferation of GC cells by impairing the METTL1/CCT2 pathway." (PMID 38389703, 2024).
head and neck cancer (2 papers, 2021). A primary or metastatic malignant neoplasm affecting the head and neck.
lymph node metastasis (2 papers, 2013 to 2019). "We found that the positive expression of CCT2 and PDIA3 was significantly associated with clinicopathological features of both SC/ASC and AC specimens, including high TNM stage and lymph node metastasis." (PMID 23782473, 2013). "Furthermore, we observed a significant correlation between the expression of CCT2 and tumor size, invasion status, and lymph node metastasis of AC as well as patient age (P < 0.05)." (PMID 23782473, 2013). "For the first time, we found that positive CCT2 expression in both SC/ASC and AC subtypes was significantly associated with clinicopathological features, including large tumor size, high TNM stage, and lymph node metastasis." (PMID 23782473, 2013). "In addition, CCT2 expression was detected more frequently in tumors with lymph node metastasis (62.1%) than those without lymph node metastasis (29.4%) (P = 0.03)." (PMID 23782473, 2013).
medulloblastoma (2 papers, 2020 to 2022). A malignant, invasive embryonal neoplasm arising from the cerebellum. "Although CCT2 has not been reported in medulloblastoma, CCT2 is significantly enriched in the WNT pathway which is closely related to the growth of medulloblastoma." (PMID 33101383, 2020).
metastatic cancer (2 papers, 2022). A carcinoma which has spread from the original site of growth to another anatomic site. "This study supports our findings that a marker like CCT2 whose expression correlates with advanced cancers could have applications for enrichment and detection of metastatic cancers that have either epithelial or mesenchymal characteristics." (PMID 35749519, 2022).
neuroblastoma (2 papers, 2022 to 2024). Neuroblastoma (NB) is the most common solid, extracranial childhood tumor. "Our results demonstrate that CCT2 could be used as a diagnostic indicator for malignant neuroblastoma cells shed into blood, using liquid biopsy protocols like the enumeration of CTCs with the CellSearch System." (PMID 36185250, 2022). "We further showed that CCT2 could be used as a diagnostic marker to identify neuroblastoma cells shed into blood." (PMID 36185250, 2022). "Given that our data support CCT as an essential enabler of the migratory phenotype in SK-N-AS and IMR-32 cells, we tested whether CCT2 could be used as a diagnostic indicator for invasive neuroblastoma cells." (PMID 36185250, 2022). "Results showed that using CCT2 for the detection of neuroblastoma cells in blood was more effective than the conventional approach of using epithelial markers like cytokeratins." (PMID 36185250, 2022). "We then determined the relative expression of CCT2 in comparison to other oncogenes, with a focus on neuroblastoma-relevant oncogenes, some of which are potential interactors with CCT (BioGRID)." (PMID 36185250, 2022). "Bioinformatic and histologic data revealed increased expression of CCT2 RNA and protein across multiple pediatric cancers, with some of the highest expression shown in neuroblastoma." (PMID 36185250, 2022). "To use the CellSearch CXC kit for investigating CCT2 in the detection of neuroblastoma cells shed in blood, we first confirmed that the IMR-32 cells express EpCAM." (PMID 36185250, 2022). "Since neuroblastoma had some of the highest CCT2 protein levels, we evaluated CCT2 by IHC in a dedicated neuroblastoma TMA." (PMID 36185250, 2022). "CCT2 plays an essential role in promoting the invasive capacity of neuroblastoma cells and thus offers the potential to act as a molecular target in the development of novel therapeutics and diagnostics for pediatric cancers." (PMID 36185250, 2022). "The use of CCT2 as a biological indicator for detection of neuroblastoma cells shed in blood was examined by spiking IMR-32 cells into human blood and using an anti-CCT2 antibody for the identification of spiked cancer cells with the CellSearch system." (PMID 36185250, 2022). "Performing exogenous expression and depletion experiments with select neuroblastoma cell lines revealed that the CCT2 subunit is essential for the CCT complex to manifest the cancer phenotype of increased migration through its protein folding activity on cytoskeletal elements." (PMID 36185250, 2022). "We next examined CCT2 expression using neuroblastoma cell lines." (PMID 36185250, 2022). "While more tumor samples for each cancer stage are needed to achieve statistical significance, this data suggests that CCT2 levels may correlate with neuroblastoma progression and be a biological indicator of disseminated or invasive disease." (PMID 36185250, 2022). "The intracellular detection of CCT2 could also be used to identify neuroblastoma cells spiked into blood, suggesting a possible application as a diagnostic for the detection and enumeration of circulating tumor cells (CTCs) shed from pediatric tumors." (PMID 36185250, 2022). "To determine whether CCT2 depletion had a similar effect on neuroblastoma cells, we used the same CCT2 shRNA system that is induced by the addition of doxy." (PMID 36185250, 2022). "Direct inhibition of CCT2, either using RNA interference or a CCT inhibitor developed by our lab, CT20p, was cytotoxic to neuroblastoma cells." (PMID 36185250, 2022).
prostate adenocarcinoma (2 papers, 2017 to 2021). "In prostate adenocarcinoma, we observed significantly increased levels of CCT2 as compared to normal prostate tissue." (PMID 29299146, 2017).
age-related macular degeneration (1 paper, 2025). Age-related loss of vision in the central portion of the retina (macula), secondary to retinal degeneration. "Age-related macular degeneration (AMD) is the leading cause of vision loss in the elderly, and the role of chaperonin containing TCP1 subunit 2 (CCT2) remains unclear." (PMID 40374738, 2025).
ciliopathy (1 paper, 2016). A genetic disorder of the cellular cilia or the cilia anchoring structures, the basal bodies, or of ciliary function. "On the other hand, the CCT2 mutation-carrying LCA patients do not exhibit the clinical manifestations of BBS or ciliopathy in this study." (PMID 27645772, 2016).
congenital cataracts (1 paper, 2024). "Finally, while mutations in CCT2 have been linked to congenital cataracts, the potential link between these mutations and defects in aggrephagy remains unexplored." (PMID 39478698, 2024).
COVID-19 (1 paper, 2025). A disease caused by infection with severe acute respiratory syndrome coronavirus 2. "Remarkably, telomere maintenance processes were observed to be one of the top biological processes activated in patients with mild COVID-19 via activation of genes such as CCT2, CCT3, CCT4, CCT5 and CCT6A." (PMID 41141600, 2025).
frontotemporal dementia (1 paper, 2025). Frontotemporal dementia (FTD) comprises a group of neurodegenerative disorders, characterized by progressive changes in behavior, executive dysfunction and language impairment, as a result of degeneration of the medial prefrontal and frontoinsular cortices. "The research on CHMP2B is mainly focused on autophagy, frontotemporal dementia and amyotrophic lateral sclerosis, suggesting that CHMP2B could be one of the targets through which CCT2 participated in autophagy and affecting the course of AMD." (PMID 40374738, 2025).
invasive ductal carcinoma (1 paper, 2022). "We stained a breast tissue microarray (TMABRN801b) containing 70 patient samples of normal, adjacent normal, and cancer-adjacent tissue (CAT) breast tissues, and ten samples of invasive ductal carcinoma (IDC) for CCT2." (PMID 35749519, 2022).
Kidney Chromophobe (1 paper, 2021). "However, CCT2 expression was significantly lower in only two types of cancers, that were, KICH (Kidney Chromophobe) and KIRC (Kidney renal clear cell carcinoma)." (PMID 33869000, 2021).
leiomyosarcoma (1 paper, 2019). An uncommon, aggressive malignant smooth muscle neoplasm, usually occurring in post-menopausal women. "Using the data from Kaplan Meier plotter and LOGpc, we noted that leiomyosarcoma patients who had an association of genomic alterations in CDK4, CCT2, and MGAT1 showed reductions in overall and disease-free survival." (PMID 32117430, 2019). "Oncomine analysis of cancer vs. normal tissue showed that cdk4, cct2, and MGAT1 were significantly overexpressed in leiomyosarcoma in the different datasets." (PMID 32117430, 2019).
multiple myeloma (1 paper, 2024). "A predictive model developed by Mohamad and others, based on five genes including CKS1B, CCT2, PRKDC, NONO, and UBE2A, successfully predicted the prognosis of patients with multiple myeloma and has been validated in several independent datasets." (PMID 39046884, 2024).
muscular disease (1 paper, 2023). Myopathy is a peripheral nervous system disease consisting of any abnormal condition or disease of the muscular tissues; commonly designates a disorder involving skeletal muscle. "This review aims to summarize what has been studied so far about the direct involvement of aggrephagy and the activation of the key players, among others, p62, NBR1, Alfy, Tollip, Optineurin, TAX1BP1 and CCT2 in muscular diseases." (PMID 37176163, 2023).
prostate tumors (1 paper, 2021). "Using polymeric nanoparticles to systemically deliver CT20p, we achieved regression of breast and prostate tumors in mice and demonstrated that CT20p directly binds to the CCT2 subunit." (PMID 33996588, 2021).
sarcoma (1 paper, 2021). A usually aggressive malignant neoplasm of the soft tissue or bone. "The highest percent of samples/patients with CCT2 gene amplification or increased gene expression is observed in soft tissue cancers like sarcoma (19% of sarcoma samples/patients have gene alterations in CCT2, TCGA)." (PMID 33996588, 2021).